HOXB13 (homeobox B13)
Diseases named in the same sentence as HOXB13 in open-access papers (continued):
Sharing a sentence is not in itself a finding about the gene and the disease.
tumor (continued). "Since SSTR1 is downregulated after ARSI, we examined the reciprocal relationship between the AR/FOXA1/HOXB13 transcription machinery and SSTR1 expression, specifically the effect of testosterone (as opposed to ADT and ARSIs) on SSTR1 expression and tumor growth." (PMID 39352383, 2024). "It is unclear whether the enriched binding sites for FOXA1, HOXB13 and CDX2 are dependent or independent of AR activity in single cells from high-grade tumours." (PMID 34911933, 2021). "Using non-carriers matched to carriers by age, race and tumor grade, we found that the relative prevalence of both ETS and PTEN alterations in 101 HOXB13 G84E carriers is significantly lower than that seen in non-carriers undergoing surgical treatment at our institution." (PMID 28186998, 2017). "Of note, the AR+ HOXB13–negative GRN in the ARhigh/PSMAlow sample showed robust STEAP1 and STEAP2 expression, suggesting that co–targeting of STEAP and PSMA in AR–positive disease may be an effective strategy to achieve broader tumor cell coverage." (PMID 38645034, 2024).
cancer (84 papers, 2007 to 2025). A tumor composed of atypical neoplastic, often pleomorphic cells that invade other tissues. "Cai Q., Wang X., Li X., Gong R., Guo X., Tang Y., Yang K., Niu Y.,Zhao Y. Germline HOXB13 p.Gly84Glu mutation and cancer susceptibility:a pooled analysis of 25 epidemiological studies with participates." (PMID 41164275, 2025). "Gene mutations exist depending on the cancer type, and HOXB13 expression in LIHC differed significantly depending on mutation status." (PMID 38792899, 2024). "Additional studies with larger sample sizes are needed to validate these results and comprehend the exact mechanism underlying the role of HOXB13 during immune invasion and cancer progression in LIHC." (PMID 38792899, 2024). "Two patients with cancer cases and the HOXB13 p.G84E mutation died up to a year after diagnosis and one was still alive by February 2021." (PMID 34983599, 2022). "In the literature there are several studies on mutation in the HOXB13 gene and association with different cancers." (PMID 34983599, 2022). "Genetic screening of cancer-prone families for the HOXB13 G84E germline mutation is now encompassed by National Comprehensive Cancer Network (NCCN) Guidelines." (PMID 34059701, 2021). "First, despite being the largest study on HOXB13, the number of G84E mutation carriers remains small in individuals with cancers other than prostate." (PMID 32830201, 2020). "Despite similar expression levels of HOXB13 in the distal colon and skin in both sexes (GTEx), increased cancer risk was observed only in males." (PMID 32830201, 2020). "One such case is the known cancer susceptibility variant G84E in HOXB13, which has been shown to have a mutation frequency approximately three-fold higher in Sweden and Finland compared to the mutation frequency in North America." (PMID 32183364, 2020). "Mendelian inheritance patterns are largely due to DNA alterations that give rise to pathogenic germline variants, or mutations in highly penetrant cancer predisposition genes such as in HOXB13 and BRCA2." (PMID 29690565, 2018). "Regarding the oncogenic potential of specific HOXB13 mutations, we here describe their involvement in different cancer-associated capabilities." (PMID 28050579, 2016). "Considering that, random-effects model was used to examine the association between HOXB13 p.Gly84Glu mutation and overall cancer susceptibility (OR = 2.872, 95% CI = 2.121−3.888, P < 0.001)." (PMID 26517352, 2015). "Numerous studies have focused on the association between the germline HOXB13 p.Gly84Glu mutation and cancer risks, however, the results are inconsistent." (PMID 26517352, 2015). "If individuals with prevalent cancer are less likely to carry the HOXB13 G84E mutation and were included preferentially due to survival bias, our results would underestimate any true associations." (PMID 25629170, 2015). "In our present study, we summarized all the effects of HOXB13 p.Gly84Glu mutation with the risk of various cancers." (PMID 26517352, 2015). "Numerous studies have investigated association between the germline HOXB13 p.Gly84Glu mutation and cancer risk." (PMID 26517352, 2015). "Strong HOXB13 staining was significantly linked to accelerated cell proliferation as measured by Ki67LI in all cancers (p < 0.0001)." (PMID 25825985, 2015). "Larger case-control studies are needed to determine if germline HOXB13 mutations predispose to a more aggressive disease and to evaluate if they significantly increase the risk of other cancers." (PMID 26176944, 2015). "Crude odds ratios (ORs) and their 95% confidence intervals (CIs) were calculated by STATA 12.1 software to evaluate the association of HOXB13 p.Gly84Glu mutation and cancer susceptibility." (PMID 26517352, 2015). "Here, we conducted the largest meta-analysis to summarize the association between HOXB13 p.Gly84Glu mutation and cancer risk through pooling all candidate studies." (PMID 26517352, 2015).
cancer (continued). "Similarly, we identified 57 potential TSGs, of which at least 13 have been implicated in cancer, including HOXB13, ZNF350, ZNF331, CNTNAP2, NEFH, and ABR with reduced expression due to hypermethylation or loss." (PMID 37245006, 2023). "In addition, homeobox (HOX) genes such as HOXB7, HOXC8, and HOXB13, which are used as PC diagnostic markers, are involved in malignant cell transformation and/or cancer progression." (PMID 36428807, 2022). "The expression of HOXB13 has been associated with the development of several cancers." (PMID 33179733, 2020). "Currently, only HoxD4 and HoxB13 have been shown to be mutation targets in limited cancers." (PMID 31137902, 2019). "Thus, our data strongly suggest that GATA2 and c‐JUN are TFs in addition to FOXA1 and HOXB13 that associate with ARBSs and regulate AR binding selectively in normal and cancer cells." (PMID 31520575, 2019). "Intriguingly, the cooperation between the rare HOXB13 mutation and other risk factors may play an important role in promoting cancer risk." (PMID 31013831, 2019). "Multiple studies reported a significant association of HOXB13 with many types of cancers." (PMID 31013831, 2019). "In addition, subgroup analyses were conducted to explore the association of HOXB13 p.Gly84Glu mutation and susceptibility to the three types of cancers." (PMID 26517352, 2015). "However, mutations within the HOXB13 gene and the linkage analyses of the neighboring 17q21–22 region found this region to be involved in the development of different cancers." (PMID 24490656, 2014). "Previous studies have shown that HOXB13 promotes these behaviors in various cancers by regulating genes involved in the epithelial–mesenchymal transition (EMT)." (PMID 41023726, 2025). "HOXB13, a member of the HOXB cluster, has been implicated in the pathogenesis and progression of various cancers." (PMID 41023726, 2025). "Overall, a germline pathogenic variant (gPV) in a cancer predisposing gene was identified in 9.7% of individuals (CHEK2, FANCM, NF1, POT1 and PTEN) and a candidate variant in 4.2% of individuals (HOXB13, MAX and RECQL4)." (PMID 39979679, 2025). "Selective Cell in ORgan Targeting (SCORT) nanoparticles are developed for precise CRISPR/Cas13d mRNA and gRNA delivery to metastatic cancer cells in vivo, aiming to knock down the undruggable oncogenic TF HoxB13." (PMID 40349174, 2025). "The SCENIC results suggest that normal and cancer epithelia share canonical luminal transcription factors (TFs) such as HOXB13, GATA2, AR." (PMID 38483933, 2024). "In contrast, dysregulated HOXB13 expression promotes androgen receptor-independent function and cancer cell proliferation." (PMID 38201640, 2024). "These proof-of-concept experiments revealed novel molecular properties of HOX interactomes and led to the identification of a novel cofactor of HOXB13 that promoted its proliferative activity in a cancer cell context." (PMID 36611993, 2023). "The model allows for personalising PCa risks on the basis of a consultand's age, detailed cancer FH, moderate- to high-risk BRCA2, HOXB13, and BRCA1 PVs, and a 268-SNP PGS." (PMID 36493335, 2023). "Using specific siRNA demonstrated that the DNA methyltransferase 3b (DNMT3b), an enzyme that plays an important role in the methylation of many cancer genes, also involved methylation of the HOXB13 promoter in DU145 cells." (PMID 33920256, 2021). "The expression of HOXB13 is increased in the submucosa or muscular layer, until the cancer tissue infiltrates into the adventitia." (PMID 34306077, 2021). "In CRC, HOXA13, HOXD13 and HOXC6 were reported to promote cancer progression, and HOXB13 was reported to suppress tumors." (PMID 34950145, 2021). "In various cancers, including PC, the HOXB13 promoter is hypermethylated, but this condition is more severe in DU145 than in LNCaP cells." (PMID 33920256, 2021). "Two known pathogenic moderate cancer risk variants were also found in participant A; in the genes CHEK2 and HOXB13." (PMID 34711244, 2021).
cancer (continued). "In malignant striated muscle tumors, HOXB13 plays a role in promoting cancer by interfering with the differentiation of mesenchymal stem cells." (PMID 33315534, 2021). "HOXB13 is observed in the progression of various cancers, and its increase is deeply involved in its activation." (PMID 31878059, 2019). "In contrast, HOXB13 is highly expressed in the skin and prostate as well as in some cancer cells in adults and is known to be involved in promoting carcinogenesis." (PMID 31878059, 2019). "For example, a large (> 10 kb) pan-cancer hypermethylated canyon is located around HOXB13, an oncogene in ovarian and breast cancers." (PMID 30097071, 2018). "In ovarian and breast cancer cell lines, HOXB13 has been shown as an oncogene involved in upregulation of estrogen receptor (ER), increase of cancer cell proliferation, and invasiveness." (PMID 30097071, 2018). "In cancers, HOXB13 staining was seen in 5,278 of our 10,216 (51.7%) interpretable tumors and was considered weak in 22.3%, moderate in 19.7% and strong in 9.6% of cancers." (PMID 25825985, 2015). "Strong PSA expression was seen in 55.1% of HOXB13-negative tumors, but only in 33.1% of cancers with strong HOXB13 expression." (PMID 25825985, 2015). "Strong HOXB13 expression was found in 17% of cancers with strong AR expression, but only in 1.3% of AR-negative tumors." (PMID 25825985, 2015). "The data from this study revealed a striking link of strong HOXB13 expression with PTEN deleted ERG positive cancers." (PMID 25825985, 2015). "The high number of cancers included in this analysis further enabled us to study the combined impact of the interrelated biomarkers HOXB13, AR, and PSA." (PMID 25825985, 2015). "HOXB13 immunostaining was detectable in 51.7% of 10,216 interpretable cancers and considered strong in 9.6%, moderate in 19.7% and weak in 22.3% of cases." (PMID 25825985, 2015). "Aberrant expression and methylation-dependent expression of the HOXB13 gene has been shown in cancer." (PMID 24490656, 2014). "Significantly, EZH2 has been reported to play a key role in mediating both histone methylation and DNA methylation of HOXB13 gene in some cancer cells." (PMID 22808286, 2012). "Significantly, EZH2 has been implicated to play a key role in mediating both histone methylation and DNA methylation of HOXB13 gene in some cancer cells." (PMID 22808286, 2012). "Like Hepsin, HOXB13 expression was overall significantly elevated in cancer tissue, although the increase was highly variable." (PMID 17280610, 2007). "Among the five patients carrying the HOXB13 X285K variant, one reported a family history of PCa (his father), while no family history of breast or other cancers was observed." (PMID 41188766, 2025). "Notably, disruption of either the TBX3or HOXB13 genes activity leads to the preferential death ofprostate cancer cell lines." (PMID 41164275, 2025). "Furthermore, flow cytometry analysis indicated a decrease in the proportion of CD133+ cells, a commonly used marker of cancer stemness, in the si-HOXB13-transfected cells." (PMID 41023726, 2025). "The transcription factor HOXB13 is a potential target forprostate cancer therapy." (PMID 41164275, 2025). "Additionally, miR-20a-5p has been found to regulate glucose metabolism in the liver by targeting and inhibiting the expression of HOXB13 (homeobox B13), a gene involved in cancer cell proliferation, invasion, and migration." (PMID 40075907, 2025). "Additional research is needed to determine what role HOXB13 plays depending on the type of cancer." (PMID 38792899, 2024). "Moreover, in cancer cells, HOXB13 promotes increased expression of AR and NKX3-1 through its central role in recruiting SWI/SNF chromatin remodelers to their cognate super-enhancers." (PMID 38201640, 2024). "We cannot state with certainty that the P/LP BRCA2, CHEK2, HOXB13, and MITF variants contributed to the patient's cancer, these might also be secondary findings." (PMID 38415346, 2024).
cancer (continued). "The mutations cluster within a conserved domain in the HOXB13 protein responsible for binding to the homeobox cofactor MEIS1, hinting that altered HOXB13-MEIS interactions might contribute to cancer promotion." (PMID 35104804, 2022). "A shared genetic basis among cancers may be supported by HOXB13’s role in embryonic development and body patterning." (PMID 25629170, 2015). "HOXB13 is overexpressed in other cancers; thus, HOXB13 may induce EMT in multiple cancers for the promotion of invasion and metastasis." (PMID 25944620, 2015). "However, other authors have suggested that HOXB13 functions as a tumor suppressor gene in prostate and other types of cancer, presumably through haploinsufficiency." (PMID 26176944, 2015). "Homeobox B13 (HOXB13) is one of the numerous DNA-binding transcription factors of the HOX gene family that has been implicated in the development of normal prostate and cancer." (PMID 25825985, 2015). "Elevated HOXB13 expression levels were strongly linked to deletions of PTEN in all cancers as well as in the subsets of ERG- negative and ERG- positive cancers (p < 0.0001 each)." (PMID 25825985, 2015). "The promoter of HOXB13 has been frequently reported to be hypermethylated in various cancers." (PMID 22808286, 2012). "However, it and our data suggested that HOXB13 plays various roles depending on the cancer type." (PMID 38792899, 2024). "In cases with mutations in the HOXB13 gene, the family history of cancer was negative." (PMID 34983599, 2022). "However, AR positive cancers appear to rely more predominantly on HOXB13 for proliferation." (PMID 31273254, 2019). "After exclusions of first-degree relatives and others in identifying all cancer cases and controls (described in the Methods section), a total of 74,625 individuals from RPGEH GERA were used to evaluate the association between the HOXB13 G84E mutation and cancer." (PMID 25629170, 2015). "HOXB13, which encodes the transcription factor 13, belongs to the HOXB gene cluster at chromosome 17, involves in embryonic development of different organs, regulates transcription of androgen receptor (AR) target genes and is reported to function as a tumor suppressor in cancer." (PMID 26517352, 2015). "Promoters’ analysis highlighted enriched transcription factor binding sites for developmental genes, such as HOX and SOX family genes (HOXB13 and SOX10), and for well-known cancer-related genes, like BRCA1." (PMID 38891761, 2024). "Among these, HOXB13 (involved in skin development) and GLDC (a component of the glycine cleavage system) are both known TSGs that are epigenetically silenced in many cancers and promote apoptosis and autophagy, respectively." (PMID 37245006, 2023). "We also checked the patient outcome data using the Cistrome cancer database for TF profiles of FOXA1, HOXB13 and CDX2 in the TCGA PRAD data set54,55." (PMID 34911933, 2021). "HOXA13, HOXD13 and HOXC6 were reported to promote cancer progression in CRC, and HOXB13 was reported to suppress tumors in CRC." (PMID 34950145, 2021). "In the remaining 56 small families without shared variants of HOXB13 and TRRAP, patients with PC from 44 families had at least one variant of cancer genes of the CGC." (PMID 27701467, 2016). "Using total RNA we did not observe a differential expression of HOXB13 between the benign and malignant tumors; this was likely due to the multifocal nature of PCa." (PMID 20504375, 2010). "Although some levels of methylation could be detected in normal tissues, methylation of HOXB13, HNF1B, and CGI 7:48 CpG islands was clearly more pronounced in intraductal carcinomas." (PMID 19250546, 2009).
cancer (continued). "Functional studies further suggested that elevated expression of HOXB13 is related to ER downregulation and, consequently, to TAM-resistance in ER+ cancers.Further research should explore whether HOX family members influence immune evasion and response to checkpoint inhibitors." (PMID 40574852, 2025). "Thus, acetylated HOXB13 at superenhancers of actively transcribed regions may act as a liaison between the SWI/SNF chromatin remodelers and the DDR machinery and benefit cancer cells following DNA damage." (PMID 38730575, 2024). "However, HOXB13 was largely unrelated to all other deletions irrespective of whether all cancers or subgroups of ERG positive or ERG negative cancers were analyzed." (PMID 25825985, 2015). "Immunoblot analysis revealed that HOXB13 is expressed in AR positive PC cell lines of luminal epithelial origin as well as in AR negative PC3, a cancer of small cell origin." (PMID 31273254, 2019). "HOXB13 expression was seen in 63.4% (ERG IHC) and 64.1% (ERG FISH) of ERG-positive cancers but in only 44.1% and 49.9% of cancers without ERG staining and ERG rearrangement, respectively (p < 0.0001 each)." (PMID 25825985, 2015).
adenocarcinoma (3 papers, 2020 to 2025). A common cancer characterized by the presence of malignant glandular cells. "Conversely, we found HOXB13 to be specifically associated with SWI/SNF in adenocarcinoma cells, and not in CRPC-NE." (PMID 33144576, 2020). "Compared to that of BPH, the intensity of HOXB13 staining was greater in adenocarcinomas with Gleason scores of 7, 8, 9, and 10 albeit not statistically significant, possibly due to the wide variations in H-score observed in both BPH and the adenocarcinomas." (PMID 33531604, 2021). "However, no significantcorrelation was found between HOXB13 and TBX3 transcriptionlevels and the overall survival of patients diagnosed withprostate adenocarcinoma." (PMID 41164275, 2025).
CNS tumors (1 paper, 2010). "Consistently low HOXB13 mRNA expression was observed in nearly all pediatric CNS tumors including GBM, LCM, MED and PA." (PMID 19793339, 2010). "Of the three genes examined, overexpression of HOXB13 was unique to MEPN, while overexpression of NEFL and PDGFRα was observed in other pediatric CNS tumors." (PMID 19793339, 2010). "In addition to MEPN and intracranial EPN, comparative gene expression analysis of HOXB13, NEFL and PDGFRα was expanded to include a variety of pediatric CNS tumors." (PMID 19793339, 2010).
hematologic malignancies (1 paper, 2025). "To further validate this finding, we performed H3K27ac ChIP-seq in control and HOXB13-KD LNCaP cells treated with either DMSO or CCS1477, a selective p300/CBP bromodomain inhibitor currently in clinical trials for advanced PCa and hematologic malignancies." (PMID 41277556, 2025).